ENSG00000207002
Synonyms: LOC124906346
Gene: Small nucleolar RNA gene on chromosome 3 (123,814,077 to 123,814,207, forward strand). Ensembl gene ENSG00000207002.
Gene Ontology:
Biological process: RNA processing
Cellular component: nucleolus
Homologues: Orthologues: rat LOC120102633 (75% identical). Paralogues in human: SNORA5A (89% identical), SNORA5B (88% identical), SNORA5C (63% identical).